OGDH (oxoglutarate dehydrogenase)
Description:
2-oxoglutarate dehydrogenase (E1o) component of the 2-oxoglutarate dehydrogenase complex (OGDHC). Participates in the first step, rate limiting for the overall conversion of 2-oxoglutarate to succinyl-CoA and CO(2) catalyzed by the whole OGDHC. Catalyzes the irreversible decarboxylation of 2-oxoglutarate (alpha-ketoglutarate) via the thiamine diphosphate (ThDP) cofactor and subsequent transfer of the decarboxylated acyl intermediate on an oxidized dihydrolipoyl group that is covalently amidated to the E2 enzyme (dihydrolipoyllysine-residue succinyltransferase or DLST). Plays a key role in the Krebs (citric acid) cycle, which is a common pathway for oxidation of fuel molecules, including carbohydrates, fatty acids, and amino acids. Can catalyze the decarboxylation of 2-oxoadipate in vitro, but at a much lower rate than 2-oxoglutarate. Can also convert 2-keto-4-hydroxyglutarate (KHG) and CoA into malyl-CoA (By similarity). Mainly active in the mitochondrion. A fraction of the 2-oxoglutarate dehydrogenase complex also localizes in the nucleus and is required for lysine succinylation of histones: associates with KAT2A on chromatin and provides succinyl-CoA to histone succinyltransferase KAT2A.
Synonyms: E1o; HsOGDH; OGDC-E1; OGDH-E1; E1k; OGDH2; KGD1; AKGDH; OGDC; OGDHD
Tractability: Small molecule: a structure with a bound ligand is known. PROTAC: UniProt records ubiquitination sites on it; ubiquitination databases record sites on it; its protein half-life has been measured.
Target class: Enzyme; Oxidoreductase
Gene: Protein-coding gene on chromosome 7 (44,606,549 to 44,709,070, forward strand). Ensembl gene ENSG00000105953.
Subcellular location: Mitochondrion; Nucleus
Subcellular location (Human Protein Atlas): Mitochondria
Pathways (Reactome):
Metabolism: Glycine degradation; OGDH complex synthesizes succinyl-CoA from 2-OG
Metabolism of proteins: Mitochondrial protein degradation
Gene Ontology:
Molecular function: oxoglutarate dehydrogenase (succinyl-transferring) activity; protein binding; thiamine pyrophosphate binding; carboxy-lyase activity; heat shock protein binding; oxidoreductase activity, acting on the aldehyde or oxo group of donors, disulfide as acceptor; protein-folding chaperone binding
Biological process: 2-oxoglutarate metabolic process; succinyl-CoA metabolic process; generation of precursor metabolites and energy; tricarboxylic acid cycle; 2-oxoglutarate decarboxylation to succinyl-CoA; cerebellar cortex development; hippocampus development; olfactory bulb mitral cell layer development; pyramidal neuron development; striatum development; tangential migration from the subventricular zone to the olfactory bulb; thalamus development
Cellular component: mitochondrion; nucleus; oxoglutarate dehydrogenase complex; mitochondrial matrix; mitochondrial membrane
Genetic constraint (gnomAD): Loss-of-function variants: 36 observed, 114.66 expected, observed/expected ratio (o/e) 0.31, 90% interval 0.24 to 0.41. The upper end of that interval is the gene's LOEUF score, 0.41, which puts it in group 1 of 6, group 1 being the genes least tolerant of losing a copy. Missense variants: 795 observed, 1,369 expected, observed/expected ratio (o/e) 0.58, 90% interval 0.55 to 0.62. Synonymous variants: 473 observed, 542.21 expected, observed/expected ratio (o/e) 0.87, 90% interval 0.81 to 0.94.
Gene-disease validity (ClinGen):
ClinGen rates the evidence that OGDH causes each of these diseases.
mitochondrial disease (autosomal recessive): Definitive.
Homologues: Orthologues: chimpanzee OGDH (100% identical), macaque OGDH (100% identical), dog OGDH (98% identical), pig OGDH (98% identical), rabbit OGDH (97% identical), rat Ogdh (96% identical), guinea pig OGDH (95% identical), mouse Ogdh (94% identical), tropical clawed frog ogdh (91% identical), zebrafish ogdhb (84% identical), Drosophila melanogaster Ogdh (61% identical), Caenorhabditis elegans ogdh-1 (56% identical), and 2 more. Paralogues in human: OGDHL (76% identical), DHTKD1 (35% identical).
Diseases named in the same sentence as OGDH in open-access papers:
OGDH is named in the same sentence as 57 diseases in open-access papers, as found by Europe PMC text mining. Sharing a sentence is not in itself a finding about the gene and the disease. The quoted sentences say what the papers report.
gastric cancer (9 papers, 2022 to 2025). A primary or metastatic malignant neoplasm involving the stomach. "Further analysis revealed that the tumor-suppressive effect of SIRT5 in gastric cancer is associated with the regulation of 2-oxoglutarate dehydrogenase (OGDH) expression." (PMID 39944690, 2025). "The levels of OGDH in gastric cancer tissues are highly upregulated compared to normal tissues, which correlates with poor clinicopathological parameters for gastric cancer patients." (PMID 37601653, 2023). "The target of ALKBH5, OGDH, has been shown to inhibit the proliferation of glioblastoma and gastric cancer cells." (PMID 37742191, 2023). "Lu and coworkers demonstrated that SIRT5 inhibited the growth and migration of gastric cancer cells by interfering with mitochondrial function and redox state through the desuccinylation of 2-oxoglutarate dehydrogenase (OGDH) and the inhibition of OGDH complex activity." (PMID 39781339, 2025). "The data suggest that the upregulation of OGDH might facilitate the forward TCA cycle to satisfy the requirement for the rapid growth of gastric cancer cells." (PMID 38197966, 2024). "In addition, the overexpression of OGDH promoted tumorigenesis of gastric cancer cells in nude mice." (PMID 37601653, 2023). "SIRT5 inhibits the activity of the oxoglutarate dehydrogenase (OGDH) complex via de-succinylation and thus suppresses the epithelial-to-mesenchymal transition (EMT) of gastric cancer cells." (PMID 36605449, 2022). "SIRT5-mediated desuccinylation of OGDH inhibits the OGDH complex’s activity, leading to reduced mitochondrial membrane potential, decreased ATP production, increased ROS levels, and altered NADP/NADPH ratios, ultimately suppressing gastric cancer progression." (PMID 39944690, 2025). "Similarly, desuccinylation inhibits 2-oxoglutarate dehydrogenase (OGDH) activity, decreases mitochondrial membrane potential, reduces ATP production, and increases ROS levels and NADP/NADPH ratio in gastric cancer (GC) cells, thereby inhibiting the growth and migration of GC cells." (PMID 39979670, 2025).
glioblastoma (6 papers, 2016 to 2024). The most malignant astrocytic tumor (WHO grade IV). "Furthermore, USP13 can deubiquitinate and stabilise ACLY/OGDH and c-Myc in ovarian cancer and glioblastoma, respectively, thereby functioning as an oncogene." (PMID 33627786, 2021).
viral infection (6 papers, 2021 to 2024). "In our research we found that RNA modification m6A-mediated downregulation of the OGDH-Itaconate pathway reprograms cellular metabolism to inhibit viral replication, proposing potential targets for controlling viral infection." (PMID 38934770, 2024). "During viral infection, the enzymatic activity of ALKBH5 is reduced in host cells, which leads to the downregulation of the α-ketoglutarate dehydrogenase (OGDH)-itaconate pathway associated with viral infection mediated by YTHDF2." (PMID 38957616, 2024). "This study provided the first evidence on the function of a particular metabolic enzyme, Oxoglutarate dehydrogenase (OGDH), in a viral infection." (PMID 34834978, 2021). "As in viral infection, ALKBH5-mediated regulation of OGDH levels regulate TCA cycle activity and impact cellular metabolic fitness." (PMID 37742191, 2023).
ovarian carcinoma (5 papers, 2018 to 2025). A malignant neoplasm originating from the surface ovarian epithelium. "Recently, we demonstrated that the inhibition of the TCA cycle utilizing the inhibitor CP1–613, which targets TCA cycle enzymes pyruvate dehydrogenase (PDHA1) and 2-oxoglutarate dehydrogenase (OGDH), significantly decreased the growth of xenografts derived from resistant ovarian cancer cells." (PMID 40386427, 2025). "USP13 gene is amplified in serious ovarian cancers and specifically deubiquitinates and thus upregulates two key metabolic key enzymes, ATP citrate lyase (ACLY) and oxoglutarate dehydrogenase (OGDH)." (PMID 35898882, 2022). "In our previous study, we identified that USP13 increased both energy production and biosynthesis in human ovarian cancer cells by stabilizing Oxoglutarate Dehydrogenase (OGDH) and ATP Citrate Lyase (ACLY), which are key metabolic enzymes driving the reprogramming of ovarian cancer cell metabolism." (PMID 35173307, 2022).
colorectal cancer (4 papers, 2016 to 2025). A primary or metastatic malignant neoplasm that affects the colon or rectum. "Only the role of AS in the gene OGDH has been reported in colorectal cancer, where an up-regulation of OGDH alternative mRNA transcript has been linked with glutamine metabolism and an increase in energy." (PMID 31100982, 2019). "Interestingly, an alternative splice variant of OGDH, which is tumour-specific, is overexpressed in colorectal cancer." (PMID 39941144, 2025). "Interestingly, Snezhkina and colleagues have demonstrated that an alternative splice variant of OGDH that is tumor specific is overexpressed in colorectal cancer." (PMID 28748451, 2018). "In colorectal cancer, OGDH is downregulated due to promoter hypermethylation, a phenomenon also observed in breast, lung, esophageal, cervical, and pancreatic cancers." (PMID 39941144, 2025). "OGDH is downregulated in colorectal cancer as the result of promoter hypermethylation and similar promoter hypermethylation has been documented in breast, lung, esophageal, cervical, and pancreatic cancer." (PMID 28748451, 2018). "Thus, we assumed that up-regulation of OGDH alternative mRNA transcript may indicate the presence of active OGDH complex in colorectal cancer that is required to control energy and glutamine metabolism." (PMID 28105922, 2016).
Alzheimer disease (3 papers, 2017 to 2021). A progressive, neurodegenerative disease characterized by loss of function and death of nerve cells in several areas of the brain leading to loss of cognitive function such as memory and language. "In autopsied patients with Alzheimer’s disease, the protein concentrations of all subunits of OGDH were reduced compared with control patients in the cortex, with the loss of the E3 subunit protein being restricted to the hippocampus." (PMID 28303258, 2017). "In a separate study, the activities of both OGDH and PDH were reduced in autopsied Alzheimer’s disease patients and were correlated with the severity of the disease." (PMID 28303258, 2017).
breast carcinoma (3 papers, 2014 to 2024). "This phenotype was specific for pyruvate production as TCA cycle genes (e.g., OGDH) were broadly essential across ER+ breast cancer cell lines (right)." (PMID 38112643, 2024).
developmental delay (3 papers, 2023 to 2025). "Subsequently, biallelic mutations in OGDH were described in six patients, all of whom exhibited global developmental delay, hypotonia, dystonia, and elevated serum lactate levels—findings consistent with OGDHC dysfunction." (PMID 41018056, 2025). "We provide a clear phenotype-genotype correlation with in silico, in vitro, and in vivo evidence to support pathogenic variants in OGDH leading to a neurodevelopmental disease characterized by global developmental delay, movement disorder, and metabolic aberrations." (PMID 36520152, 2023). "OGDH, as one of the rate-limiting enzymes in the TCA, plays a pivotal role by catalyzing an irreversible process within this metabolic pathway, which is linked to conditions such as developmental delays, hypotonia, movement disorders, metabolic disturbances, obesity, and diabetes." (PMID 38693536, 2024).
glioma (3 papers, 2022 to 2024). A benign or malignant brain and spinal cord tumor that arises from glial cells (astrocytes, oligodendrocytes, ependymal cells). "We found that the IDH mutation exerted a more substantial impact on α-KG homeostasis in glioma cells with low OGDH expression, resulting in enhanced effects on α-KG-associated differentiation and epigenetic changes." (PMID 39872214, 2024). "In both astrocytes and glioma cells with low OGDH expression, the IDH mutation markedly disrupts α-KG homeostasis, resulting in metabolic reprogramming, epigenetic alterations, and differentiation blocks." (PMID 39872214, 2024). "Immunoblotting and immunohistochemical (IHC) staining confirmed that OGDH expression was remarkably low in IDH-mutated gliomas." (PMID 39872214, 2024). "Our findings reveal that low expression of OGDH is a common metabolic characteristic of IDH-mutated gliomas and mature astrocytes." (PMID 39872214, 2024). "In this study, we found that low expression of oxoglutarate dehydrogenase (OGDH) was a common feature in IDH-mutated gliomas, as well as in astrocytes." (PMID 39872214, 2024). "Through metabolomics, we found that the reduction of TCA metabolites in IDH-mutated glioma cells with low OGDH expression was more significant compared to that in control cells, but TCA cycle enzymes were not significantly altered." (PMID 39872214, 2024). "Consistently, IF staining results showed that the IDH1 mutation significantly decreased 5-hmC levels in OGDH-silenced glioma cells, and immunoblotting data showed that the IDH1 mutation significantly elevated H3K27me3 and H3K4me3 levels in the OGDH-silenced U87 cells." (PMID 39872214, 2024). "Low OGDH expression should be regarded as a metabolic hallmark of IDH-mutated gliomas." (PMID 39872214, 2024). "By analyzing The Cancer Genome Atlas (TCGA) data, we found that OGDH mRNA levels were significantly downregulated in IDH-mutated gliomas compared with other TCA cycle enzymes, including citrate synthase (CS), succinate dehydrogenase complex subunit B (SDHB), and fumarate hydratase (FH)." (PMID 39872214, 2024). "In IDH-mutated gliomas, we found that low OGDH expression is an intrinsic characteristic." (PMID 39872214, 2024). "Additionally, we observed that a mutant IDH1 inhibitor significantly raised α-KG levels and aided the differentiation of IDH1-mutated glioma cells with low OGDH expression." (PMID 39872214, 2024). "Our findings from the TCGA database also indicated that patients with low OGDH expression tended to have better prognostic characteristics, suggesting that the favorable prognosis in glioma patients with low OGDH expression may be attributed to the accompanying IDH mutation." (PMID 39872214, 2024). "Crucially, the IDH1 mutation has a more pronounced effect on disturbing α-KG homeostasis in glioma cells with low OGDH expression." (PMID 39872214, 2024). "Then, we knocked down OGDH in U87 and U251 glioma cells using lentivirus-mediated short-hairpin RNA (shRNA)." (PMID 39872214, 2024). "The disturbed α-KG homeostasis resulted in an increase in glutaminolysis and a decrease in transamination in glioma cells with low OGDH expression, which served as a compensatory mechanism to maintain α-KG turnover." (PMID 39872214, 2024). "Due to the fact that glioma originates from glial cells in the central nervous system (CNS), we examined the expression of OGDH in the brain." (PMID 39872214, 2024). "Collectively, this study reveals that low OGDH expression is a crucial metabolic characteristic of IDH-mutant gliomas, providing a potential strategy for the treatment of IDH-mutant gliomas by targeting α-KG homeostasis." (PMID 39872214, 2024). "In glioma cells (U87 and U251), we found that the OGDH expression was relatively higher than in astrocytes, which was consistent with observations based on human IDH-WT glioma samples." (PMID 39872214, 2024).
glioma (continued). "These metabolic alterations implied that the effects of the IDH1 mutation on disturbing α-KG-related amino acid metabolism were more significant in glioma cells with low OGDH expression." (PMID 39872214, 2024). "Six genes of these essential TrMGs, including MAOB, HSD17B10, KYNU, AOX1, and OGDH, were determined as hazardous factors for glioma patients, and other two genes (CYP2E1 and ALDH2) were identified as protective factors." (PMID 36386216, 2022). "Consequently, we found an increase in the expression of GFAP, but a decrease in the expression of Nestin and two markers of glioma stem cells, CD133 and CD44, indicating that low expression of OGDH promotes glioma cell differentiation." (PMID 39872214, 2024). "Moreover, immunoblotting results also indicated that the IDH1 mutation increased GLUD1 expression in OGDH-silenced U87 cells, which was consistent with the changes observed in IDH-mutated gliomas." (PMID 39872214, 2024). "Low OGDH expression promoted the differentiation of glioma cells by increasing α-KG levels." (PMID 39872214, 2024). "Therefore, we postulate that lowering OGDH expression is likely to diminish the stemness and encourage differentiation of GSCs, and targeting OGDH expression and activity could be a viable strategy in glioma treatment." (PMID 39872214, 2024). "Moreover, our results also indicated that reduced OGDH expression can promote the differentiation of glioma cells, while IDH1 mutations impeded the differentiation of glioma cells with low OGDH by reducing the accumulation of α-KG and increasing glutaminolysis." (PMID 39872214, 2024). "Importantly, our results suggest that targeting α-KG homeostasis could be a potential approach for treating IDH-mutant gliomas with low expression of OGDH." (PMID 39872214, 2024). "In summary, we demonstrate that OGDH expression is diminished in mature astrocytes and IDH-mutant gliomas." (PMID 39872214, 2024).
primary biliary cholangitis (3 papers, 2023 to 2024). Primary biliary cholangitis (PBC) is a chronic and slowly progressive cholestatic liver disease of autoimmune etiology characterized by injury of the intrahepatic bile ducts that may eventually lead to liver failure. "Studies in mouse models of PD have implicated mitochondrial proteins as potential antigens, particularly the mitochondrial matrix protein, OGDH, which is implicated in the autoimmunity-linked disorder primary biliary cholangitis." (PMID 38405939, 2024).
cervical cancer (2 papers, 2020 to 2022). A primary or metastatic malignant neoplasm involving the cervix. "For example, the presence of aconitase 2 (ACO2), IDH1, the subunit G of the IDH3 complex (IDH3G), oxoglutarate dehydrogenase (OGDH) subunit from the oxoglutarate dehydrogenase complex (OGDC) in the nucleus has been described using the human cervical cancer cells HeLa." (PMID 36299478, 2022).
diabetes (2 papers, 2015 to 2024). "We found also gain in copy number of OGDH in RCC+diabetes and in RCC patients." (PMID 25821562, 2015).
leukemia (2 papers, 2014 to 2023). A malignant (clonal) hematologic disorder, involving hematopoietic stem cells and characterized by the presence of primitive or atypical myeloid or lymphoid cells in the bone marrow and the blood. "Future studies may be necessary to dissect the relative contributions of OGDH and previously reported pathways, especially as leukemia treatments targeting the m6A epitranscriptome are being developed." (PMID 37742191, 2023).
lung carcinoma (2 papers, 2011 to 2021). "The survival analysis was not significant between mutation and wild-type groups of OGDH in lung cancers (p > 0.05)." (PMID 34970420, 2021).
melanoma (2 papers, 2023 to 2025). A malignant, usually aggressive tumor composed of atypical, neoplastic melanocytes. "In particular, CPI613, a lipoic acid analog that inhibits PDHA1 and OGDH, has been shown to dramatically attenuate the progression of melanoma and improve the therapeutic efficacy of anti-PD-1 against this tumor." (PMID 40721981, 2025). "Similarly, other enzymes regulating the TCA cycle, such as pyruvate dehydrogenase subunit 1 (PDHA1) and oxoglutarate dehydrogenase (OGDH), are found to be hyperactivated in melanoma, highlighting the importance of citrate metabolism in shaping the tumor metabolic landscape." (PMID 40721981, 2025). "In melanoma cells with suppressed SIRT3, OGDH expression was found reduced." (PMID 37844995, 2023).